APOBEC3B (apolipoprotein B mRNA editing enzyme catalytic subunit 3B)
Diseases named in the same sentence as APOBEC3B in open-access papers (continued):
Sharing a sentence is not in itself a finding about the gene and the disease.
breast cancer (continued). "In addition, we detected an amplified APOBEC3B gene locus in 309 (17.26%) breast cancers." (PMID 27552096, 2016). "Taken together, our data suggests that tumour-infiltrating immune cells may be an important feature of breast cancers arising in women with APOBEC3B germline deletion, and that this may be of particular interest in Asian women where the germline deletion is more common." (PMID 27233495, 2016). "First, we evaluated whether the calculated APOBEC3B copy number values could predict the clinical outcome of first-line tamoxifen therapy in a cohort of 329 hormone-naive breast cancer patients with ER-positive primary breast cancer." (PMID 27552096, 2016). "The observation that the APOBEC3B deletion polymorphism does not seem to have any impact on the clinical outcome for breast cancer patients, whereas increased expression of APOBEC3B mRNA does, strengthens the evidence that there are two different molecular mechanisms in place." (PMID 27552096, 2016). "However, we did not observe any association between germline APOBEC3B status and the clinicopathologic features of breast cancer patients." (PMID 27233495, 2016). "The same study also demonstrated through comparison of mutation spectra that APOBEC3B and/or APOBEC3A were most likely responsible for the breast cancer hypermutation patterns, but allowed the possibility that other APOBEC3s might also contribute to genome mutation." (PMID 26861772, 2016). "However, we did not observe the immune scores to be significantly different across APOBEC3B copy number in the smaller sample set of breast cancers from TCGA with A3Bdel/del, A3Bdel/wt, and A3Bwt/wt breast cancers with median immune scores of −45, 273 and −13, respectively." (PMID 27233495, 2016). "Although the APOBEC3B deletion polymorphism does not have any prognostic or predictive value, it does appear to contribute to breast tumorigenesis by conferring an increased risk to develop breast cancer." (PMID 27552096, 2016). "Thus, in contrast to APOBEC3B mRNA levels, the APOBEC3B deletion polymorphism has neither a prognostic nor a predictive value for breast cancer patients." (PMID 27552096, 2016). "However, only 14 APOBEC3B-null breast cancers could be identified for analysis and tumor ages were unknown, making mutation frequency comparisons difficult." (PMID 25848704, 2015). "Moreover, a recent study from Burns and co-workers demonstrated that APOBEC3B mRNA is overexpressed in most primary breast tumors and breast cancer cell lines analyzed and that expression and activity of APOBEC3B correlated with genomic uracil levels, dC>dT transition rates and mutation frequencies." (PMID 26097867, 2015). "In breast cancer, for example, PTEN depletion and HER2 amplification have been shown to induce replication stress and increase APOBEC3B activity in vitro." (PMID 36978147, 2023). "The similarity of yeast and breast cancer kataegis as well as increased APOBEC3B and APOBEC3A expressions in breast cancer samples are highly suggestive for the role of APOBEC3B and/or APOBEC3A in the breast cancer hypermutation." (PMID 36405752, 2022). "The APOBEC3B protein expression level was higher in renal clear cell carcinomas, UCEC, HNSC, PAAD and LIHC and lower in breast cancers and LUAD (all P < 0.01) than in normal tissues." (PMID 35918642, 2022).
breast cancer (continued). "This is the first study evaluating APOBEC3B levels within DCIS and co-existing IBC, including different breast cancer subtypes." (PMID 31357602, 2019). "Aberrant expression of APOBEC3B has also been shown to be induced by DNA viruses such as HPV, specifically in breast cancer." (PMID 29404275, 2018). "Moreover, a deletion polymorphism in the APOBEC3B gene cluster on chromosome 22 is associated with elevated breast cancer risk and a specific APOBEC mutation pattern has been described in a number of cancers, including breast cancer, suggesting a functional link with cancer development." (PMID 29404275, 2018). "We observed ρ between − 0.118 and − 0.049, padj > 0.94 (n = 43, Ntests = 26,110) for correlations of both APOBEC3B and APOBEC3A expression levels with log(IC50) of tamoxifen in breast cancer cell lines." (PMID 29642934, 2018). "In conclusion, here we demonstrate the relationship between APOBEC3B mRNA expression and sensitivity to NAC, and its role as a predictive factor for pCR in breast cancer patients receiving NAC." (PMID 30093965, 2018). "Given that APOBEC3B expression is upregulated in breast tumours, and that its upregulation is associated with APOBEC-associated mutational signatures, it has been suggested that APOBEC3B may be an endogenous source of mutations in cancers, especially breast cancer." (PMID 27233495, 2016). "We examined APOBEC3A, APOBEC3B and APOBEC3G mRNA expression levels in a panel of 15 breast cancer cell lines (five luminal, five basal and five HER2+) by quantitative PCR." (PMID 27634334, 2016). "In conclusion, our integrated analyses suggested that APOBEC3B and APOBEC3C expression patterns were correlated with ER status and clinical outcome, providing an additional implication that these two genes may contribute to mutation profile and clinical outcome in breast cancer subtypes." (PMID 26682542, 2015). "Also copy number variations affecting the APOBEC3 gene cluster on chromosome 22 might be important in breast cancer, since a germline copy number polymorphism, in which the gene-coding region of APOBEC3B is deleted and its 3′ UTR joined to APOBEC3A, associates with elevated risk of breast cancer." (PMID 26097867, 2015). "For example, APOBEC3B and APOBEC3C show low DNA methylation levels (median methylation ratio ≤20 %) in both HMEC and ER− breast cancer cells, although a slight increase in ER− cancer cells." (PMID 26682542, 2015). "In breast cancer, studies have detected enrichment of APOBEC3A, APOBEC3B, and APOBEC3H." (PMID 36978147, 2023). "Given that APOBEC3B induces G/C-to-A/T mutation in human cancers including breast cancer and is upregulated in DLBCL, we compared the level of APOBEC3B protein in R/R and non-R/R DLBCL samples by immunohistochemistry." (PMID 35592333, 2022). "Interestingly, breast cancer cell lines were among the cancer types with positive correlation between APOBEC3A and APOBEC3B expression." (PMID 29642934, 2018). "We also did not see an association of the APOBEC3B deletion with familial breast cancer cases, which were selected from the GDANSK and SZCZECIN breast cancer cases [OR (95%CI)=1.06(0.82-1.36), p=0.67]." (PMID 29100317, 2017). "The frequency of the APOBEC3B deletion in breast cancer cases does not significantly differ from that observed in population controls in GDANSK[OR(95%CI)=1.31(0.94-1.82), p=0.11)] or SZCZECIN [OR(95%CI)=0.89(0.74-1.07), p=0.20]." (PMID 29100317, 2017). "The copy number analyses in the adjuvant setting, except for the ER-negative LNN analysis, had sufficient power to conclude that there is no or only a marginal prognostic effect of APOBEC3B copy numbers in breast cancer patients." (PMID 27552096, 2016). "As Kanu and colleagues show, APOBEC3A is barely detectable in breast cancer cell lines and was not increased by the stimuli that induced APOBEC3B." (PMID 27716362, 2016).
breast cancer (continued). "We have performed APOBEC3B copy number analyses among 1,756 primary breast cancers and found no copy number change among 1,260 breast cancers." (PMID 27552096, 2016). "Three-group comparison across APOBEC3B copy number for macrophages M2 fractions was not significant with A3Bdel/del, A3Bdel/wt, and A3Bwt/wt breast cancers with mean fractions of 0.179, 0.197 and 0.207, respectively." (PMID 27233495, 2016). "We compared gene expression profiles of breast cancers arising from APOBEC3B deletion carriers and non-carriers using microarray analyses." (PMID 27233495, 2016). "Why APOBEC3B expression would only be prognostic in ER + and not in ER − breast cancer is unclear, especially because expression is higher in ER − disease." (PMID 25123150, 2014). "Our analysis of breast cancer cell lines, however, was not able to replicate the previously reported correlation of APOBEC3B expression level in vivo with resistance to tamoxifen in a clinical setting or in murine xenograft models in ER+ breast cancer due to the lack of statistical significance." (PMID 29642934, 2018). "Moreover, high APOBEC3B mRNA expression was a predictive factor for pCR and APOBEC3B mRNA expression level did not correlate with breast cancer prognosis for patients receiving NAC." (PMID 30093965, 2018). "This might imply that the higher APOBEC3B mRNA levels we found in breast cancer brain and ovarian metastases are independent of the micro-environment at these locations." (PMID 28141868, 2017). "Thus, besides not having any prognostic value, APOBEC3B copy numbers also do not appear to have a predictive value for breast cancer patients." (PMID 27552096, 2016). "Thus, APOBEC3B and/or APOBEC3A are the deaminases likely responsible for the breast cancer hypermutation although it remains possible that other APOBEC3s might contribute to genome mutation in other tumours." (PMID 23599896, 2013).
viral infection (18 papers, 2014 to 2025). "Other studies show that the loss of the APOBEC3B gene can increase susceptibility to viral infection, as in infections by HIV, HBV, and HPV." (PMID 36980505, 2023). "APOBEC3B is a cytosine deaminase implicated in immune response to viral infection, cancer predisposition and carcinogenesis." (PMID 27233495, 2016). "APOBEC3B facilitates the formation of protein-RNA condensates with stress granule assembly factor (G3BP1) by protecting mRNA associated with stress granules from RNAse L-induced RNA cleavage during viral infection." (PMID 36781883, 2023). "Higher incidence may be explained by the likelihood that APOBEC3B null cells are predicted to be more susceptible to viral infection and insertional mutagenesis by endogenous elements, which this protein normally serves to suppress." (PMID 25123150, 2014). "Nuclear inclusions disperse APOBECs due to the densely tessellated virions, which suggests APOBEC3B induction in cells with late-stage viral infection." (PMID 41337590, 2025). "Although the mechanism of the upregulation of APOBEC3B mRNA expression has not been been fully elucidated, a recent study showed the induction of APOBEC3B in vitro by environmental factors such as DNA damage and viral infection." (PMID 27977754, 2016). "This research hinted APOBEC3B could affect viral infection via not only editing viral genome but also regulating host innate immunity response." (PMID 38105291, 2023). "Overall, the available data indicate that although dissociation of Rb/E2F complexes by early proteins carrying the LXCXE motif is an important mechanism involved in APOBEC3B induction during viral infection, additional signals are likely to be required for high level APOBEC3B expression." (PMID 36146883, 2022). "As part of the innate immune system, which plays a key role in combating exogenous infection especially viral infection, APOBEC3B expression is stimulated by a complex network of innate immune responses involving components such as interferons, interleukins, and Toll-like receptors." (PMID 29853799, 2018). "The function of APOBEC3B that may play a role in selective pressure may be its potential involvement in response against viral infections, e.g., HBV or HTLV1 infection, or its suggested role in innate immunity against malaria." (PMID 29100317, 2017). "APOBEC3B, a member of the AID/APOBEC family, is part of the innate immune system which plays a key role in combating exogenous infection especially viral infection." (PMID 29853799, 2018). "Low pre-treatment levels of APOBEC3A have been reported previously, and expression of both APOBEC3B and APOBEC3A has been reported to increase in response to cancer cell treatment with DNA-damaging agents or as part of cellular interferon-induced transcriptional response to viral infections." (PMID 29642934, 2018). "The HIV-1 protein Vif promotes viral infection by counteracting APOBEC3G and F. However, Vif does not seem to have the same effect on other members of the APOBEC3 family, such as APOBEC3B and H, which also limit HIV-1 replication." (PMID 37515266, 2023).
breast tumors (17 papers, 2014 to 2023). "Significantly, we found a higher percentage of Asian breast tumours with Signature 13, consistent with the higher prevalence of the APOBEC3B germline deletion polymorphism among the population (p = 0.0486)." (PMID 33353943, 2020). "Apolipoprotein B mRNA editing enzyme catalytic polypeptide-like 3B (APOBEC3B) is a gene editing enzyme with cytidine deaminase activity and high expression of its mRNA in breast tumors have been shown to be associated with progressive cases and poor prognosis." (PMID 30093965, 2018). "Notably, in these studies, high APOBEC3B expression levels were only associated with poor prognosis for ERα-positive primary breast tumors." (PMID 28141868, 2017). "Second, a series of biochemical experiments was done with the catalytic domain of APOBEC3B to deduce its intrinsic DNA cytosine deamination preference or ‘signature’ in vitro, and this was shown to closely resemble the actual cytosine mutation pattern in breast tumors." (PMID 25848704, 2015). "Previous studies investigated APOBEC3B mRNA expression in primary breast tumors and paired normal tissue." (PMID 28141868, 2017). "Taken together, these data showed that APOBEC3B is significantly and constitutively upregulated in a large proportion of breast tumors and cancer cell lines." (PMID 25848704, 2015). "Clinical characteristics of breast tumors in carriers of the APOBEC3B mutation and non-carriers were similar." (PMID 37510234, 2023). "To test this hypothesis, we quantified APOBEC3B mRNA levels using reverse-transcriptase-quantitative PCR (RT-qPCR) in a large series of primary breast tumors and asked whether expression levels correlate with disease outcome." (PMID 25123150, 2014). "Third, the antiviral DNA cytosine deaminase apolipoprotein B messenger RNA (mRNA) editing enzyme catalytic polypeptide-like 3B (APOBEC3B) was shown to be overexpressed in cell lines and primary breast tumors and responsible for elevated levels of genomic uracil and mutations in cell lines." (PMID 25123150, 2014). "Results based on our study do not support the hypothesis that the germline APOBEC3B deletion polymorphism is the driving force for immune activation in breast tumors." (PMID 31856876, 2019). "To conclude, we propose that, using a robust hybrid FS method, the present study identified a robust and optimal set of three gene biomarkers (MAPK 1, APOBEC3B, and ENAH) for detecting the primary breast tumors of BC patients." (PMID 36832196, 2023). "In this study, the hybrid-based FS pipeline screened an optimal subset that includes three gene biomarkers, namely MAPK1, APOBEC3B, and ENAH, for earlier detection of primary breast tumors." (PMID 36832196, 2023). "In the real-time online primary breast tumor detector, the users can classify primary breast tumor samples from normal breast samples using the gene expression values of the genes, namely MAPK-1, APOBEC3B, and ENAH actin regulator (ENAH)." (PMID 36832196, 2023). "Overall, APOBEC3B mRNA levels of distant metastases were significantly higher as compared to the corresponding primary breast tumor (P = 0.0015), an effect that was not seen for loco-regional lymph node metastases (P = 0.23)." (PMID 28141868, 2017). "A recent study showed that 5’-TC biased mutations and kataegis are still prevalent in a small number of breast tumors in the complete absence of APOBEC3B." (PMID 25848704, 2015).